CXCL12 (C-X-C motif chemokine ligand 12)
Diseases named in the same sentence as CXCL12 in open-access papers (continued):
Sharing a sentence is not in itself a finding about the gene and the disease.
tumor (continued). "In particular, the CXCR4/CXCL12 axis has been involved in metastasis formation, increased survival of cancer cells under harsh conditions, and establishment of a tumour promoting cytokine/chemokine network." (PMID 17925864, 2007). "While increasing evidence has suggested the pivotal role of CXCL12/CXCR4 biological axis in tumor metastasis, the specific mechanisms regulating CXCR4 expression in different tumors are poorly understood." (PMID 17083723, 2006). "Sites that exhibited a high propensity for tumor metastasis and high levels of CXCL12 exhibited intense CD164 immunoreactivity." (PMID 16859559, 2006). "Recent publications on CXCR4 are in line with the ‘homing’ theory as CXCR4 expression comediates dissemination of primary tumours to different organs through the chemotactic factors CXCL12." (PMID 16819541, 2006). "Although the distribution and biology of CXCR7 remains to be elucidated, it is possible that CXCR7 plays a role in CXCL12-mediated tumor metastasis." (PMID 17083723, 2006). "We found that animals bearing the human tumor cell lines treated with neutralizing anti-CXCL12 antibodies resulted in markedly reduced metastases to the lungs, adrenal glands, liver and circulation (buffy coat), as compared to control antibody treated groups." (PMID 17083723, 2006). "A recent review suggested recruitment of ASCs from ppWAT into PCa cells and the TME are precursors to tumor stromal cells and cancer‐associated fibroblasts and a source of IL‐6, TNFα, CXCL1, CXCL5, CXCL8, CXCL12, MCP‐1, and leptin facilitating tumor angiogenesis and cancer cell proliferation." (PMID 41450167, 2026). "In summary, signaling and functional assays in CRC cell lines showed that PDGF-BB–mediated PDGFRβ activation remodels the secretome of tumor-associated fibroblasts—especially by increasing the release of CCL5 and CXCL12—thereby promoting CRC cell proliferation and migration." (PMID 41601676, 2026). "Indeed, pharmacological disruption of this axis using AMD3100, a CXCR4 antagonist, significantly reduced both IL-1β and CXCL12 secretion, prevented adipocyte reprogramming, and suppressed tumor cell proliferation." (PMID 42316277, 2026). "However, autophagy in CAFs promotes tumor development via providing nutrients (L-lactate, ketone bodies), cytokines (IL-1β, IL-6, IL-8), CXCL12, and α-SMA in advanced stages of tumorigenesis." (PMID 41328341, 2026). "CXCL12 plays a key role in regulating the interaction between the tumor and the TME." (PMID 40142155, 2025). "Inhibiting the CXCL12/CXCR4 axis may provide a strategy to limit tumor growth and prevent metastasis in patients with CRC." (PMID 40426863, 2025). "The HGF/MET pathway is classically recognized as a primary initiator of “invasive growth” and EMT driven by stromal paracrine signaling, whereas the CXCL12/CXCR4 axis predominantly functions as a “chemotactic compass” guiding tumor cell homing to specific organs like the bone and lung." (PMID 41514604, 2025). "Similarly, engineering NSCs to express higher levels of chemokine receptors, such as CXCR4 and c-Met, augments their responsiveness to tumor-derived chemotactic signals (e.g., CXCL12, hepatocyte growth factor), thereby enhancing tumor tropism." (PMID 41264121, 2025). "CAFs isolated from human tumor tissues secreted higher levels of CXCL12 compared to NFs5,28." (PMID 40849508, 2025). "Additionally, the TCGA database indicated significantly higher expression of CLDN1 and INHBA, while CXCL12 displayed lower expression between COAD tumor and control samples, consistent with our analysis results of the DEGs, DEMs, and DMRs." (PMID 40426863, 2025). "For example, CXCL9/CXCR3, which is known to recruit cytotoxic T cells, may counteract the tumor‐promoting effects of CXCL12/CXCR4 by enhancing anti‐tumor immunity." (PMID 40145607, 2025).
tumor (continued). "Furthermore, stromal cells in the tumor microenvironment, including MMP3+IL24+ fibroblasts, APLN+ endothelial cells, and CXCL12+ pericytes, were implicated in ESCC metastasis through angiogenesis, collagen production, and inflammatory responses." (PMID 39741182, 2025). "Moreover, triptolide inhibits CXCL12 gene expression within the tumor microenvironment, leading to the suppression of the CXCL12/CXCR4 axis and a reduction in TAM infiltration." (PMID 40490812, 2025). "PDAC-derived CXCL12 can induce the infiltration of SCs into the tumor site." (PMID 40248695, 2025). "Moreover, CXCL12 secretion promotes tumor infiltration by immunosuppressive regulatory T cells, tumor-associated macrophages, and myeloid-derived suppressor cells, thereby blocking the activation of the immune system against the tumor." (PMID 40307933, 2025). "Stromal cells in the tumour microenvironment secrete CXCL12, which in turn binds to the CXCR4 receptor on the cancer cell and activates many signalling pathways (e.g., PI3K/AKT and MAPK) that promote tumour cell proliferation, tumour cell migration, the EMT, and even metastasis." (PMID 41002447, 2025). "The prolonged effect of CXCL12 on GC progression could be attributed to its role in creating a tumor-permissive microenvironment, facilitating sustained tumor growth and dissemination over time." (PMID 40481962, 2025). "Furthermore, CXCL12 expressed by tumor-activated LECs in both axillary LN and lung can also attract CXCR4-expressing melanoma CSCs, thereby promoting metastatic growth." (PMID 40740784, 2025). "Additionally, a combination of AMD3100 (a CXCL12/CXCR4 axis inhibitor) and anti-PD-1 therapy significantly reduces tumor growth, suggesting that circ_0020710 contributes to immune evasion through the CXCL12/CXCR4 signaling axis." (PMID 40739089, 2025). "Elevated levels of CXCL12 and/or CXCR4 in the blood have been associated with higher tumor grades and may indicate resistance to treatment, making it a candidate for monitoring therapeutic efficacy." (PMID 40134607, 2025). "In addition, they stimulate cytokine release from leukocytes, endothelial cells, and tumor cells, increasing local levels of IL-8, CXCL12, and CCL2, which support tumor cell proliferation and angiogenesis." (PMID 40723273, 2025). "Importantly, the CXCL12/CXCR4 axis has become an important drug target for tumor therapy due to its critical role in cancer stem cell maintenance." (PMID 41445742, 2025). "Additionally, HMGA2 promotes tumor progression by regulating macrophage proliferation, migration, polarization and angiogenesis via CXCL12/CXCR4-dependent mechanisms." (PMID 40351420, 2025). "Notably, CXCL12-mediated signaling concurrently promotes tumor angiogenesis, thereby coupling immune evasion with pro-tumorigenic processes." (PMID 40534854, 2025). "CXCL12 plays a crucial role in immune cell trafficking and tumor suppression." (PMID 40898538, 2025). "CXCL12 promotes angiogenesis and contributes to tumor progression." (PMID 40943634, 2025). "Moreover, homologous aquaporins, such as AQP3, are known to be upregulated at the migrating edge of cancer cells upon stimulation with CXCL12, further implicating aquaporins in chemokine-driven tumor invasion." (PMID 41324079, 2025). "Additionally, Tc17 cells stimulate the release of the chemokine CXCL12 from tumor cells, which in turn recruits CXCR4+ MDSCs." (PMID 40452847, 2025). "Concurrently, a cluster of chemokines (e.g., chemokine ligand 22 [CCL22]; and C‐X‐C motif chemokine ligand 12 [CXCL12]) are secreted to promote recruitment and infiltration of immunosuppressive cell populations, creating a permissive environment for tumor proliferation and metastatic dissemination." (PMID 41427020, 2025). "CLDN1, INHBA, and CXCL12 may serve as clinically relevant biomarkers in CRC, particularly as prognostic indicators linked to tumor progression, immune modulation, and metastatic potential." (PMID 40426863, 2025).
tumor (continued). "Investigating how CXCL12 interacts with other components of the tumor microenvironment, such as immune cells and stromal fibroblasts, may also uncover novel therapeutic targets." (PMID 40481962, 2025). "A high tumor expression of CXCL12 was defined as the positive tumor expression of CXCL12 in five studies, the presence of CXCL12 in > 5% or > 30% of cancer cells in two studies, and the presence of CXCL12 above median density value in another three studies." (PMID 40481962, 2025). "CAF-derived CXCL12 is believed to promote T cell chemotaxis and sequester them within the peritumoral stroma, thereby restricting their infiltration into tumor nests, impairing effective antitumor immunity, and ultimately contributing to poor clinical outcomes." (PMID 40849508, 2025). "In terms of tumor metastasis, CXCR6 signaling stimulated the transformation of mesenchymal stem cells into cancer-associated fibroblasts, which secreted stroma-derived factor 1, also known as CXCL12." (PMID 41347146, 2025). "In tumor samples, CXCL-12, VCAM-1, and ICAM-1 levels negatively correlated with surgery duration." (PMID 40652770, 2025). "Besides, many past studies on tumor cell metastasis in microfluidic chips focused on biochemical signal-induced migration, such as the chemotactic migration of tumor cells induced by epidermal growth factor and CXCL12 chemokine." (PMID 40510151, 2025). "CXCL12 expression was detected in the cytoplasm of stromal cells adjacent to tumor cells." (PMID 40849508, 2025). "Tumor cells, CAFs, and others may secrete CXCL12 and activate the CXCR4 receptor, which directs tumor cells to specific sites and promotes metastatic and neovascular growth." (PMID 41376630, 2025). "Moreover, iCAFs showed interaction with surrounding T cells by secreting IL-6 and CXCL12, leading to establishment of a tumour-favourable microenvironment in gastric cancer." (PMID 39780187, 2025). "CXCL12 sensitizes cells to anoikis and minimizes tumor progression in normal tissue." (PMID 40397803, 2025). "In fact, it has been seen that patients with low CXCR4 expression in cytotoxic T lymphocytes in peripheral blood have a better efficacy to anti-PD-1 ICIs in NSCLC because probably they are receiving trafficking orders from a higher expression of CXCL12 in tumor tissue." (PMID 41149503, 2025). "Furthermore, our analysis of the correlation between tumor stage and CXCL12 expression revealed a progressive decrease in CXCL12 expression in early stages (e.g. BLCA, STAD, LUAD, etc.)suggesting its potential role in early tumor detection." (PMID 40166682, 2025). "The CXCL12/CXCR4 axis has been confirmed to regulate tumor metastasis in different tumors." (PMID 41142609, 2025). "Thus, high CXCL12 levels in the TME provide paracrine signaling through a feedback loop that mediates integrin b1 accumulation on the tumor cell surface, promotes tumor EMT, and prevents apoptosis through tumor cell upregulation of CXCR4." (PMID 40485724, 2025). "CXCL12 expression reduces in initial stages of tumor during our study on its staging correlation, including BLCA, STAD, LUAD, LIHC, COADREAD, CESC,HNSC, BRCA, OV and UCEC indicating that CXCL12 potentially offers substantial clinical utility for diagnosing these tumors at an early stage." (PMID 40166682, 2025). "Moreover, local fibroblasts, which are considered a major source of CAFs, can be stimulated by autocrine/paracrine CXCL12, and CAFs can induce tumor progression through direct and indirect effects." (PMID 39801758, 2025). "The CXCL12/CXCR4 axis plays a significant role in tumour cell dormancy and metastasis in TNBC." (PMID 41002447, 2025). "The expression of CXCL12 in CAFs can affect tumor growth and metastasis." (PMID 41584584, 2025). "In addition, FGFR signaling regulates the chemokine system; for instance, it upregulates CXCR4 expression, thereby enhancing tumor cell chemotaxis toward CXCL12." (PMID 41514604, 2025).
tumor (continued). "In response to tissue damage and inflammation in TME, CAFs attract polymorphonuclear leukocytes by secreting CXCL12, which in the presence of tumor-derived CCL20, additionally upregulate PD-L1 expression in neutrophils consequently inhibiting antitumor activity of T cells." (PMID 40940764, 2025). "Complementary single-cell-ST atlases corroborate a chemoresistance-associated peri-vascular niche populated by SOX9+ stem-like tumour cells and immunoregulatory CAF subsets expressing CXCL12, illuminating how spatial confinement coordinates lineage plasticity and immune suppression." (PMID 40740859, 2025). "A clinical trial is exploring the combination of NOX-A12, a CXCL12 antagonist, with pembrolizumab in PDAC to enhance NK cell recruitment and improve immune responses by both directly targeting the tumor-promoting chemokine CXCL12 and releasing the brakes on the immune system." (PMID 39859231, 2025). "Moreover, immunosuppressive cytokines such as TGF-β and CXCL12 in the tumor microenvironment inhibit T-cell penetration and activity, further hindering the effectiveness of bsAbs in these tumors." (PMID 40352940, 2025). "Furthermore, CAF-derived CXCL12 facilitates tumor cell intravasation and metastasis by increasing vascular permeability and promoting leaky tumor vasculature." (PMID 40641933, 2025). "When these interventions were combined, tumor weight and volume were significantly reduced, supporting the hypothesis that simultaneous disruption of the CXCL12/CXCR4 axis and IL-2 modulation could reshape immune functionality within the TME." (PMID 40698080, 2025). "In addition, CXCL12, produced by either CAFs and tumours, misdirect CTLs to the stromal area, preventing their effective targeting and elimination of cancer cells." (PMID 40361472, 2025). "The association between CXCL12 expression in the tumor stroma and prognosis was not investigated in this study owing to the limited sample size and variable tumor types." (PMID 40849508, 2025). "Moreover, CAFs actively modulate immune responses by expressing immunomodulatory molecules such as PD-L1, and by secreting chemokines like C-X-C Motif Chemokine Ligand 12 (CXCL12) which exclude cytotoxic immune cells from the tumor core." (PMID 41179287, 2025). "High CXCL12 expression is associated with lymph node metastasis and poor survival, and the CXCL12/CXCR4 axis facilitates the recruitment of regulatory T-cells and M2 macrophages that support tumor immune escape." (PMID 40426863, 2025). "CXCL12 contributes to the formation of a tumor-supportive micro-environment by recruiting immune cells, fibroblasts, and endothelial cells, which can aid in tumor growth and metastasis." (PMID 40426863, 2025). "Conversely, M2 macrophages predominantly facilitate tumor progression by activating endothelial cell responses to growth factor signaling via CXCL12, IL-1β, IL-8, and Sema4d, thereby leading to the upregulation of angiogenesis-related genes and enhanced vascularization." (PMID 40563367, 2025). "Indeed, CXCL12 recruits regulatory B cells (Bregs) to the tumour site, where they suppress T-cell activity." (PMID 40361472, 2025). "This suggests that low circulating CXCR4+ CD8+ T cells might lead to increased tumor infiltration by lymphocytes in response to CXCL12 signaling in tumor cells, creating a proinflammatory environment." (PMID 41149503, 2025). "Importantly, CXCL12 also plays a pivotal role in recruiting immunosuppressive cells, such as Tregs and myeloid-derived suppressor cells, into the tumor microenvironment, thereby fostering immune evasion and resistance to chemotherapy." (PMID 40698080, 2025). "In CXCL12-positive stroma, T cells are more abundant in the stromal area than in the tumor nests." (PMID 40849508, 2025). "Moreover, CXCL12 can modulate the recruitment and function of immune cells, affecting the immune state of the tumor microenvironment." (PMID 41346595, 2025).
tumor (continued). "However, CXCL12 can also promote tumor metastasis by facilitating the migration and invasion of tumor cells." (PMID 41376630, 2025). "Tumors with higher CXCL12 density may exhibit a more aggressive biological behavior, leading to increased tumor proliferation, invasion, and metastasis." (PMID 40481962, 2025). "Moreover, tumor-conditioned monocytes from healthy donors acquired an NCM-like phenotype and displayed enhanced migration toward CCL5/CXCL12, suggesting recruitment into the tumor-associated macrophage pool." (PMID 41219641, 2025). "Additionally, the CXCR4/CXCL12 axis has an important role in the remodelling of the tumour microenvironment (TME)." (PMID 41002447, 2025). "Tumor expression of CXCL12 was evaluated with immunohistochemistry (IHC) in all studies except one study, in which reverse transcription-polymerase chain reaction (RT-PCR) was used to evaluated the expression of CXCL12." (PMID 40481962, 2025). "CXCL12 plays a crucial role in the intravasation of tumor cells into blood vessels." (PMID 40656546, 2025). "Additionally, CXCL12 promotes tumor angiogenesis and recruits new vascular endothelial cells, thereby increasing vascular permeability and further facilitating tumor cell entry into the bloodstream." (PMID 40656546, 2025). "DPP4i has the potential to regulate tumor growth and metastasis by acting on CXCL12." (PMID 40001479, 2025). "Neutralizing antibodies against CXCL12 can also inhibit tumor growth." (PMID 40890855, 2025). "iCAFs contribute to immune evasion by releasing pro-inflammatory cytokines and directly influencing pancreatic cancer cells to facilitate tumor progression; their secretion of CXCL12 may also support TLS formation by lymphocyte recruitment." (PMID 40784879, 2025). "In triple-negative breast cancer (TNBC), CAFs recruit monocytes to the tumor site through the CXCL12/CXCR4 axis and facilitate the progression of monocytes to immunosuppressive stabilin 1 (STAB1)+ lipid-associated macrophages, which are related to resistance to PD-1 blockade." (PMID 40453088, 2025). "Accordingly, 767 (56.4%) patients had high tumor expression of CXCL12." (PMID 40481962, 2025). "Likewise, the presence of KITLG and CXCL12 in Dox-EVs aligns with pathways involved in stem cell niche activation and tumor–stromal crosstalk." (PMID 40943445, 2025). "We evaluate emerging targeting approaches, including selective depletion of tumor‐promoting subsets (e.g., fibroblast activation protein+ CAFs), epigenetic reprogramming toward antitumor phenotypes, and inhibition of CXCL12/CXCR4 or transforming growth factor‐beta signaling pathways." (PMID 40656546, 2025). "Negative relationships between CXCL12 and key biological processes such as cell cycle, DNA damage/repair, epithelial-to-mesenchymal transition (EMT), hypoxia, invasion, metastasis, proliferation, and quiescence suggested potential tumor suppressor roles for CXCL12." (PMID 40166682, 2025). "Notably, CXCR4, a chemokine receptor expressed on the majority of plasma cells, interacts with its ligand CXCL12, a chemokine secreted by cells constituting the tumor microenvironment, especially the BMMSCs." (PMID 40296907, 2025). "Notably, CXCL12’s gene alteration across various tumor tissues was assessed using this platform; amplifications being the most prevalent." (PMID 40166682, 2025). "Notably, MMP1-mediated MSCs tumor tropism depends on interaction with extrinsic signaling CXCL12/CXCR4." (PMID 40676710, 2025). "Additionally, while serum CXCL12 levels were elevated in bothDec1+/+ andDec1−/− tumor-bearing mice compared with their respective controls,Dec1+/+-4T1 mice exhibited significantly higher CXCL12 levels thanDec1−/−-4T1 mice." (PMID 40420604, 2025). "Similarly, lncRNA SNHG17 acts as a sponge for miR-23a-3p and upregulates levels of CXCL12, contributing to an immunosuppressive tumor microenvironment." (PMID 41154428, 2025).